ENSG00000251605 (NADH dehydrogenase )
Gene: Processed pseudogene on chromosome 5 (78,307,503 to 78,307,914, forward strand). Ensembl gene ENSG00000251605.
Diseases named in the same sentence as ENSG00000251605 in open-access papers:
ENSG00000251605 is named in the same sentence as 93 diseases in open-access papers, as found by Europe PMC text mining. Sharing a sentence is not in itself a finding about the gene and the disease. The quoted sentences say what the papers report.
breast carcinoma (10 papers, 2009 to 2025). "In mtSNP-subset analysis, the gene MT-CO2 (P = 0.001, q = 0.09) in Complex IV (cytochrome c oxidase) and MT-ND2 (P = 0.004, q = 0.19) in Complex I (NADH dehydrogenase (ubiquinone)) were significantly associated with breast cancer risk." (PMID 31577800, 2019). "Our study encourages the development of compounds that inhibit NADH dehydrogenase for a personalized therapy against HR(+)/HER2(−) breast cancer." (PMID 39873399, 2025). "NDUFB9 is a component of NADH dehydrogenase in the respiratory chain complex I. NDUFB9 was downregulated in highly metastatic breast cancer and silencing its expression in MDA-MB-231 cells promotes proliferation, migration, and invasion." (PMID 38283944, 2023). "The enrichment of KIRP is mainly related to the oxidative respiratory chain, in which inhibition of NADH dehydrogenase activity has been proven to promote gastric cancer and breast cancer." (PMID 31850211, 2019). "For example, enhancement of complex I activity through NADH dehydrogenase expression strongly interferes with tumor growth and metastasis, while inhibition of complex I enhances the metastatic potential of already aggressive breast cancer cells." (PMID 25546457, 2014).
Parkinson disease (8 papers, 2012 to 2025). A progressive degenerative disorder of the central nervous system characterized by loss of dopamine producing neurons in the substantia nigra and the presence of Lewy bodies in the substantia nigra and locus coeruleus. "Ksel found a heteroplasmic mtDNAG5460A missense mutation in the ND2 subunit gene of NADH dehydrogenase was three times more frequent in Parkinson cases (4/21) compared to controls (5/77)." (PMID 39789452, 2025). "NDUFC2, the most significant novel gene from brain tissue, encodes a subunit of the mitochondrial membrane respiratory chain NADH dehydrogenase that is associated with mitochondrial diseases including Parkinson’s disease." (PMID 33809961, 2021). "NADH dehydrogenase is the first enzyme of the mitochondrial electron transport chain, and disruption of this pathway has been implicated in Parkinson’s disease." (PMID 22912838, 2012).
diabetes (5 papers, 2007 to 2023). "It has also been described, that impaired activity of the NADH dehydrogenase, due to pathogenic mtDNA mutation, occurs in people with type 2 diabetes mellitus." (PMID 36860523, 2023). "Metformin is an approved drug for the treatment of type 2 diabetes mellitus (DM) and is known to be a reversible inhibitor of mitochondrial NADH dehydrogenase, resulting in lower ATP production." (PMID 35740222, 2022). "NDUFA4, formerly known as a constituent of NADH dehydrogenase, was recently identified as a component of the CIV complex associated with mitochondrial dysfunction, syndromic obesity, and the development of diabetes." (PMID 32258168, 2020). "Genes involved in NADH dehydrogenase (ubiquinone) activity, glutamate dehydrogenase [NAD(P)+] activity, transposase activity, guanylate cyclase inhibitor activity were upregulated both in diabetes and obesity." (PMID 18078524, 2007).
Leber hereditary optic neuropathy (5 papers, 2015 to 2025). Leber's hereditary optic neuropathy (LHON) is a mitochondrial neurodegenerative disease affecting the optic nerve and often characterized by sudden vision loss in young adult carriers. "This situation is similar to the organ specific effect of mutations in mt tRNAIle, which primarily cause hypertrophic cardiomyopathy and of mutations in NADH dehydrogenase causing Leber’s hereditary optic neuropathy." (PMID 28267784, 2017). "This gene is one of the seven mitochondrial genes encoding for subunits of NADH dehydrogenase where variants in this gene have previously been associated with Leber optic atrophy, mitochondrial complex 1 deficiency, and Leigh syndrome due to mitochondrial complex deficiency." (PMID 35699875, 2022). "Leber Hereditary Optic Neuropathy (LHON) mostly occurs as a result of one of the three-point mutations in mtDNA located at nucleotides 11,778, 14,484 and 3460, all affecting the NADH dehydrogenase (ND) subunits of complex I of the electron transport system (ETS)." (PMID 39858655, 2025).
Alzheimer disease (4 papers, 2019 to 2023). A progressive, neurodegenerative disease characterized by loss of function and death of nerve cells in several areas of the brain leading to loss of cognitive function such as memory and language. "As a case in point, excitatory neurons and inter-neurons down-regulate genes encoding subunits of the NADH dehydrogenase early in the course of Alzheimer’s disease, a phenomenon that can be imaged with [18F]FP1OP, originally developed for cardiac imaging." (PMID 37957176, 2023). "On the contrary, in the cerebral cortex, energy metabolism (oxidative phosphorylation, NADH dehydrogenase activity), Alzheimer disease, and retrograde endocannabinoid signaling involve downregulated proteins." (PMID 31201651, 2019).
Leigh syndrome (4 papers, 2012 to 2022). A progressive neurological disease defined by specific neuropathological features associating brainstem and basal ganglia lesions. "NADH Dehydrogenase (Ubiquinone) Fe-S protein 4 (Ndufs4) is one of the subunits of mitochondrial complex I and its mutation in human is associated with Leigh syndrome." (PMID 34040028, 2021). "Patients with Leigh syndrome are carrying specific point mutations in the mitochondrially encoded subunits 1–6 of NADH dehydrogenase, cytochrome c oxidase and ATPase." (PMID 25839158, 2015).
Sepsis (4 papers, 2014 to 2023). Sepsis is defined as life-threatening organ dysfunction caused by a dysregulated host response to infection. "Parkin overexpression also prevented a sepsis-induced decrease in the content of mitochondrial subunits of NADH dehydrogenase and cytochrome C oxidase." (PMID 32545383, 2020). "RPCR targeting a mtDNA-specific gene sequence of NADH dehydrogenase detected a ~1.5-fold-increase of mtDNA that were released into the myocardial cytoplasm in response to sepsis." (PMID 26448624, 2015). "In particular, the prominence of NADH dehydrogenase activity in the top gene networks is consistent with decreased complex I gene expression and activity noted in skeletal muscle in human adult sepsis." (PMID 25410281, 2014). "We observed that the sepsis-alone group and the ARDS group shared 7 enriched GO functions and pathways, and showed concordant regulatory direction, such as neutrophil mediated immunity, NADH dehydrogenase complex assembly and dopaminergic related pathways." (PMID 37443002, 2023).
malaria (3 papers, 2010 to 2019). Malaria is a serious and sometimes fatal disease caused by a parasite that commonly infects a certain type of mosquito which feeds on humans. "In malaria parasites DPI has been shown to inhibit the activity of NADH dehydrogenase-an equivalent of complex I, and effectively inhibit the growth of P. falciparum in cell culture." (PMID 20221395, 2010). "Their data suggested that mitochondria of malaria parasites were able to oxidize NADH and an active NADH dehydrogenase(s) was present." (PMID 30964863, 2019). "In contrast, malaria parasites lack the conventional multi-subunit Complex I. Instead, they have a type II NADH dehydrogenase (NDH2), which is a single subunit, non-proton pumping protein, likely attaching to the mitochondrial inner membrane and facing the mitochondrial matrix." (PMID 30964863, 2019).
myocardial infarction (3 papers, 2020 to 2025). Gross necrosis of the myocardium, as a result of interruption of the blood supply to the area, as in coronary thrombosis. "The finding that Rb1 can bind to NADH dehydrogenase in mitochondrial complex I was also verified in the mice model of acute myocardial infarction." (PMID 40682486, 2025).
Non-alcoholic fatty liver disease (3 papers, 2022 to 2024). "The enrichment analysis results of GO and KEGG indicate that TBRG4 may be related to Non-alcoholic fatty liver disease, Oxidative phosphorylation, structural constituent of ribosome, NADH dehydrogenase (ubiquinone) activity." (PMID 38347489, 2024).
tuberculosis (3 papers, 2012 to 2023). A chronic, recurrent infection caused by the bacterium Mycobacterium tuberculosis. "Combining GaMF1.39 with the NADH dehydrogenase inhibitor clofazimine, the cyt-bcc:aa3 inhibitor Telacebec, or the F-ATP synthase inhibitor TBAJ-876 showed enhanced whole ATP synthesis inhibition and anti-tuberculosis activity." (PMID 37982630, 2023). "tuberculosis also responds to hypoxia in vitro and chronic infection in the mouse lung by switching from a proton-pumping to a non-proton-pumping NADH dehydrogenase." (PMID 23029022, 2012).
colon cancer (2 papers, 2005 to 2012). "Furthermore, NADH dehydrogenase (ubiquinone) has also been determined by others to have a decreased abundance in HT-29 human colon cancer cells following exposure for 24 h to 150 μM quercetin." (PMID 15748282, 2005).
gastric cancer (2 papers, 2019 to 2023). A primary or metastatic malignant neoplasm involving the stomach. "In addition, MF analysis in GO also confirmed that γ-T3 inhibits NADH dehydrogenase activity and oxidoreduction-driven activity of active transmembrane transporters pathways acting in gastric cancer cells." (PMID 37055846, 2023).
glioma (2 papers, 2008 to 2019). A benign or malignant brain and spinal cord tumor that arises from glial cells (astrocytes, oligodendrocytes, ependymal cells). "In a recent study, we described that glycolytic glioma cells are resistant to blockers of the ETC, in particular rotenone, a complex I (NADH dehydrogenase) blocker." (PMID 18985161, 2008).
mitochondrial encephalomyopathies (2 papers, 2015 to 2021). "Mutations in NADH dehydrogenase (ND) subunits of complex I lead to mitochondrial encephalomyopathies associated with various phenotypes." (PMID 25550170, 2015).
Obesity (2 papers, 2007 to 2021). Accumulation of substantial excess body fat. "We identified several variants of the NADH dehydrogenase subunit that were significantly positively or negatively correlated with risk of obesity." (PMID 33659027, 2021). "NADH dehydrogenase is required for energy generation in the cell; therefore, variants within its seven encoding genes could result in metabolic disorders including obesity." (PMID 33659027, 2021).
schizophrenia (2 papers, 2011 to 2019). A major psychotic disorder characterized by abnormalities in the perception or expression of reality. "For example, NADH dehydrogenase was up-regulated here and has previously been reported as upregulated in schizophrenia posterior hippocampal post-mortem samples but reduced in anterior hippocampus." (PMID 21347362, 2011).
amyloidosis (1 paper, 2017). A disorder characterized by the localized or diffuse accumulation of amyloid protein in various anatomic sites. "In cells undergoing WH1(A31V)-mCh amyloidosis, the only differentially induced NADH-dehydrogenase at the early stage was NdhII (encoded by ndh)." (PMID 28421043, 2017).
anaemia (1 paper, 2018). "Future studies with a larger sample size are needed to verify whether or not NADH dehydrogenase mutations might contribute to intolerance to severe anaemia." (PMID 30545357, 2018).
Arthritis (1 paper, 2019). Inflammation of a joint. "The diminution of NADH dehydrogenase caused by arthritis amounted to 31%." (PMID 31618993, 2019). "In addition to isocitrate dehydrogenase, adjuvant-induced arthritis also modified the activities of other respiratory enzymes, namely NADH dehydrogenase, L-malate dehydrogenase and succinate dehydrogenase." (PMID 31618993, 2019).
asthenozoospermia (1 paper, 2022). "-Removal of several mitochondrial genes: ATP8 (lost with 7599 bp only), ATP6, cytochrome oxidase (COX) III, cytochrome b (CYB), NADH dehydrogenase (ND) 3,4, 4L, 5, and 6.-Reduction in the obtained energy, which in turn has a negative effect on sperm flagellum movement and leads to asthenozoospermia." (PMID 35885965, 2022).
bipolar disorder (1 paper, 2021). A disorder of the brain that causes unusual shifts in mood, energy, activity levels and the ability to carry out day-to-day tasks. "Deficits in the electron transport chain complex proteins I and IV, NADH dehydrogenase and c-oxidase, respectively, were dysregulated in both AD and bipolar disorder, along with a host of other neuropsychiatric complications." (PMID 33920138, 2021).
cyst (1 paper, 2022). A sac-like closed membranous structure that may be empty or contain fluid or amorphous material. "While we show that in vitro bradyzoites develop tolerance toward the dual alternative NADH dehydrogenase and DHOD inhibitor HDQ43,68, other mETC inhibitors, such as atovaquone appear to have some effect and lead to a decrease in cyst counts in brains of latently infected mice." (PMID 35246532, 2022).
Desminopathy (1 paper, 2024). "GSEA identified overall downregulated mitochondrial-related pathways such as the tricarboxylic acid cycle, mitochondrial electron transport, and NADH dehydrogenase activity, which was similar to desminopathy." (PMID 39239540, 2024).
dilated cardiomyopathy (1 paper, 2022). Cardiomyopathy which is characterized by dilation and contractile dysfunction of the left and right ventricles. "Specifically, doxorubicin has high affinity towards mitochondrial enzymes such as xanthine oxidase, NADH dehydrogenase, and cytochrome P450 reductase to generate reactive oxygen species during dilated cardiomyopathy." (PMID 38125869, 2022).
Hypoglycemia (1 paper, 2010). A decreased concentration of glucose in the blood. "Deficiencies in seven NADH dehydrogenase genes all lead to hypoglycemia, confirmed in simulation, and a decreased ability to oxidize citrate and glutamate, reactions important for indirect renal reabsorption of citrate and glutamate in the model." (PMID 20957118, 2010).
infarction (1 paper, 2021). A localised pathological necrosis of tissue resulting from obstruction of the blood supply usually by a thrombus, an embolus, or vascular torsion. "Our results showed only discreet effects during the cardiotoxic ISO action on the endogenous cardiac NADH dehydrogenase activity, since only after 2 and 4 days of treatment (in the post-infarction stage), was observed an enhancement and a tendency to increase the maximal NADH oxidation." (PMID 34573076, 2021).
iron deficiency (1 paper, 2011). "To evaluate the magnitude of the imbalance between the fatty acid oxidation and the ETC created by iron deficiency and a high fat diet, we measured the enzyme activities of LCAD and the iron containing, electron transport chain enzyme NADH dehydrogenase." (PMID 21589859, 2011).
left ventricular hypertrophy (1 paper, 2023). Enlargement of the LEFT VENTRICLE of the heart. "A dysfunction of NADH dehydrogenase, the mitochondrial Complex I (CI), associated with the development of left ventricular hypertrophy (LVH) in previous experimental studies." (PMID 37558995, 2023).
liver cancer (1 paper, 2025). An epithelial or non-epithelial malignant neoplasm that arises from the liver. "Among the activities of the ETC complexes, the NADH dehydrogenase activity of CI was critical for cell proliferation in breast and liver cancer cells." (PMID 39873399, 2025).
lung adenocarcinoma (1 paper, 2015). A carcinoma that arises from the lung and is characterized by the presence of malignant glandular epithelial cells. "In lung adenocarcinoma cell line (A549), nonsense and missense mitND6 gene mutations resulted in significant decrease in NADH dehydrogenase activity, increases in ROS production and promoted cell migration and invasion." (PMID 25934296, 2015). "Since ND6 is a subunit of the NADH dehydrogenase, we detected the effect of mitND6 gene nonsense and missense mutation on the activity of NADH dehydrogenase in lung adenocarcinoma cells." (PMID 25934296, 2015). "Our data suggest that mitND6 gene nonsense and missense mutation might promote cell migration and invasion in lung adenocarcinoma, probably by NADH dehydrogenase deficiency induced over-production of ROS." (PMID 25934296, 2015). "Hence, mitND6 gene nonsense and missense mutation resulted in reduced NADH dehydrogenase activity in lung adenocarcinoma cells." (PMID 25934296, 2015). "Based on these findings, we propose that mitochondrial ND6 gene nonsense and missense mutation may contribute to the metastasis of lung adenocarcinoma by reducing the activity of NADH dehydrogenase and in turn the over-production of ROS probably through AKT and ERK1/ERK2 signal pathway." (PMID 25934296, 2015).
lung carcinoma (1 paper, 2023). "A substantial decrease in the activity of NADH dehydrogenase and complex I protein content has been reported in renal and lung cancer, and a reduction in the activity of complex I was also reported in thyroid cancer which was related to ND1 gene." (PMID 37482618, 2023).
multiple myeloma (1 paper, 2025). "Within this pathway, the cyclooxygenase and NADH dehydrogenase (NDUF) gene families comprised many of the genes expressed at a higher level in LCE-multiple myeloma, also factors associated with worse survival." (PMID 39699274, 2025).
neuroblastoma (1 paper, 2025). Neuroblastoma (NB) is the most common solid, extracranial childhood tumor. "Nevertheless, previous study reported that MT1A tranduced into the mitochondria of MPP+-treated SH-SY5Y neuroblastoma cells was able to alleviate mitochondrial damage, as shown by restored ATP levels, mitochondrial NADH dehydrogenase activity and mitochondrial superoxide levels." (PMID 39959428, 2025).
neuropathy (1 paper, 2024). A disorder affecting the nervous system that manifests with pain, tingling, numbness, and/or muscle weakness. "The mt-Nd3 and mt-Nd4l genes predict the activation of NADH dehydrogenase (ubiquinone) activity in mitochondria, which is associated with mitochondrial function and regulation of neuropathy." (PMID 39796522, 2024).
pancreatitis (1 paper, 2025). Inflammation of the pancreas. "Single-cell transcriptomic profiling (GSE188819) revealed significant enrichment of the NADH dehydrogenase activity pathway (FDR<0.01) in pancreatitis-associated macrophages, mechanistically linking mitochondrial ROS generation to disease progression." (PMID 41208897, 2025).
papillary thyroid carcinoma (1 paper, 2021). "The results showed that the expression levels of NADH dehydrogenase, ATP synthetase 6, cytochrome oxidase B, and cytochrome oxidase I and III genes are upregulated in papillary thyroid carcinoma, whereas the expression of nuclear encoded mtTFA is not significantly changed." (PMID 34568328, 2021).
Pleural effusion (1 paper, 2025). The presence of an excessive amount of fluid in the pleural cavity. "For pleural effusion, BL and EP tumor cells had higher expression of mitochondria-associated genes, such as CO (cytochrome C oxidase), ND (NADH dehydrogenase), and ATP6, while LP cells expressed EMT-associated genes, such as YEATS4, MDM2, and RGS5." (PMID 39955556, 2025).
toxoplasmosis (1 paper, 2021). A parasitic disease contracted by the ingestion or fetal transmission of toxoplasma gondii. "In addition, the present study detected several points of mutation of mtDNA including NADH dehydrogenase (ND1, ND4) and Cyt B genes and the nDNA pyruvate kinase (PK) gene for autistic children infected with toxoplasmosis." (PMID 33731054, 2021).
type 1 diabetes (1 paper, 2022). "The aim of the study was to evaluate the presence of Complex I in serum by measuring NADH dehydrogenase [ubiquinone] iron–sulfur protein 8 serum level, and the relationship with insulin resistance in type 1 diabetes." (PMID 36135178, 2022).